IL1B (interleukin 1 beta)
Diseases named in the same sentence as IL1B in open-access papers (continued):
Sharing a sentence is not in itself a finding about the gene and the disease.
urticaria (12 papers, 2013 to 2026). A vascular reaction of the skin characterized by erythema and wheal formation due to localized increase of vascular permeability. "In addition, previous research has established that aberrant NLRP3 inflammasome activation in masts cell contributes to histamine-independent urticaria by production of IL-1β in cryopyrin-associated periodic syndromes (CAPSs)." (PMID 35371000, 2022). "However further studies are necessary to define a pathogenic role of IL-1β, IL-1RA, and IL-18 in urticaria." (PMID 24490166, 2013). "However, further studies should be conducted on a large population to define a possible pathogenic role of IL-1β, its antagonist receptor IL-1RA and IL-18 in urticaria." (PMID 24490166, 2013). "While the detailed molecular mechanisms of pathogenic variants may vary, these mutations lead to excessive IL-1β release, causing symptoms of episodic fever, urticaria, arthralgia, and fatigue, which are typically triggered within hours of cold exposure and are mostly self-limiting." (PMID 41451028, 2026). "The inflammasome-related cytokine IL-1β was also significantly upregulated in patients with urticaria." (PMID 38539560, 2024). "Further, this pilot study highlighted that different cutAEs can manifest with distinct cytokine profiles, such as IL-18 and IL-1β being elevated in patients presenting with urticaria." (PMID 38539560, 2024). "Supporting this, mast cells have been demonstrated to recruit neutrophils, for example, via CXCL-1 during tissue inflammation, or IL-1β in urticaria." (PMID 35558068, 2022). "Serum levels of IL-1β, IL-1 receptor antagonist (IL-1RA), and IL-18 were measured in 56 children with urticaria and in 41 healthy subjects." (PMID 24490166, 2013). "Very little is known about the role of interleukin-1β (IL-1β) and interleukin-18 (IL-18) in urticaria." (PMID 24490166, 2013). "In our study, despite low levels, in children with single episode of urticaria IL-1β correlated with CRP and D-dimer levels (marker of coagulation pathway activation)." (PMID 24490166, 2013). "However, some cytokine signatures in the current study were tailored to specific clinical manifestations, e.g., patients with urticaria show a significant increase in plasma concentrations of IL-18 and IL-1β compared to other cutAEs." (PMID 38539560, 2024). "These triggers activate innate immunity, CD4 + lymphocytes, and the production of IL-1β, IFN-γ, and TNF-α, which subsequently induce cell damage and apoptosis, which are key mechanisms for the development of angioedema and/or urticaria." (PMID 34906225, 2021). "In children with single episode of urticaria, level of IL-1RA correlated with C-reactive protein (CRP), D-dimer, and IL-1β levels." (PMID 24490166, 2013). "In children with single episode of urticaria serum concentration of IL-1RA correlated with CRP, D-dimer, and IL-1β levels (r = 0.379, P = 0.019; r = 0.66, P = 0.001; and r = 0.34, P < 0.05, resp)." (PMID 24490166, 2013). "For example, the patient’s cold-induced urticaria-like rash, fever, arthralgia, and progressive SNHL, accompanied by enhanced monocyte NLRP3 signaling and IL-1β production, corresponded with the features of disorders caused by autosomal dominant NRLP3 gain-of-function mutations." (PMID 41168503, 2025). "We documented that IL-1β and IL-1RA level in infected and noninfected children with urticaria correlate differently with D-dimer and the markers of inflammation including CRP and WBC." (PMID 24490166, 2013). "Moreover, IL-1RA level was correlated with IL-1β level, CRP, and D-dimer levels in children with single episode of urticaria and WBC and D-dimer concentration in children with the recurrence of urticaria." (PMID 24490166, 2013). "In contrast, in children with single episode of urticaria without infection a positive correlation between IL-1β serum level and WBC was found (r = 0.5; P < 0.02)." (PMID 24490166, 2013).
urticaria (continued). "The possible role of IL-1β and IL-18 in acute spontaneous urticaria has not been studied in children yet." (PMID 24490166, 2013). "Moreover, correlation between serum IL-1β level and CPR and D-dimer levels in children with single episode of urticaria was found (r = 0.4, P < 0.05; r = 0.35, P < 0.05, resp)." (PMID 24490166, 2013). "In addition, children with recurrent urticaria without infection presented a positive correlation of IL-1RA concentration with WBC and IL-1β level (r = 0.7, P < 0.002; r = 0.8, P < 0.01, resp)." (PMID 24490166, 2013).
varicocele (12 papers, 2015 to 2025). A condition characterized by the dilated tortuous veins of the spermatic cord with a marked left-sided predominance. "Their study found that serum and seminal plasma NLRP-3 and IL-1β levels in patients with varicocele or azoospermia were significantly higher than in those without either condition." (PMID 39712014, 2024). "According to the previous study, proinflammatory cytokines such as IL-1α and IL-1b increased 11 and 13 wk after varicocele induction, respectively." (PMID 37727396, 2023). "They found that IL-1β expression was also increased upon the progression of varicocele, especially in Leydig cells, Sertoli cells, and spermatogonia." (PMID 37476898, 2023). "It has been demonstrated that the semen of varicocele patients contains higher levels of several inflammatory cytokines, such as interleukin (IL)-6, IL-1b, and tumor necrosis factor-alpha." (PMID 37727396, 2023). "In our previous work, we detected NLRP3, apoptosis-associated speck-like protein containing a caspase recruitment domain (ASC), and IL-1b in the semen of varicocele patients." (PMID 37727396, 2023). "To evaluate the effect of lycopene on inflammation after varicocele in testis, we detected IL-1β and IL-2 by ELISA." (PMID 34055003, 2021). "On the contrary, both Se and PDRN treatment reduced caspase-1 and IL-1β levels in testes of varicocele animals (p < 0.0001 versus varicocele)." (PMID 33525681, 2021). "Our datashowed that IL-1β was significantly increased (P=0.03)in seminal plasma of varicocele patients in comparisonwith control subjects [optic densitometry (OD)=1 ± 0.016vs." (PMID 32112635, 2020). "In varicocele,it has been also suggested that expression of IL-1α and IL-1β, as proinflammatory cytokines, wereincreased." (PMID 28868836, 2017). "IL-1β generates severe oxidative stressin different tissues and its compensatory up-regulationin varicoceles testes is well known." (PMID 26246871, 2015). "Overexpression of IL-1β in varicoceles can result ina remarkable increase of reactive oxygen species(ROS) levels which can cause an inflammatoryresponse detrimental to testicular tissue." (PMID 26246871, 2015). "Although we could not detect any significant changes in the level of expression of the NLRP3 inflammasome before the 12th wk, changes were reported in NLRP3, caspase-1, and IL-1b mRNA levels 2 months after varicocele induction." (PMID 37727396, 2023). "Lycopene improved the hypoxia-induced testicular injury by inhibiting the expression of PROK2 and decreasing levels of IL-1β and IL-2, which might show us a novel and promising treatment for varicocele testicular injury." (PMID 34055003, 2021). "Additionally,concentration of IL-1β was higher in varicocele versuscontrol subjects, whereas IL-18 was decreased in seminalplasma of varicocele patients and caspase-1 was notchanged." (PMID 32112635, 2020). "Thus, we saw that the IL1-β value in semen increased significantly with varicocele status." (PMID 37476898, 2023). "In varicocele animals, lower testosterone levels, testes weight, NLRP3 inflammasome, IL-1β and caspase-1 increased gene expression were demonstrated." (PMID 33525681, 2021). "Men with UGIs showed a significantly higher IL-1β concentration (10.0 ± 5.6 pg/mL) compared with fertile men (2.8 ± 1.7, p = 0.02), but it was not significantly different from men with varicocele (6.6 ± 3.3, p = 0.3)." (PMID 38137566, 2023). "The serum level of IL-1β was also significantly reduced in ZYP-treated rats, suggesting that ZYP may act as an NLRP3 inhibitor, suppressing the IL-1β-dependent inflammatory response in the testicles of varicocele-affected rats." (PMID 40429786, 2025). "Serum and semen NLRP3, IL1β, TAS, TOS, and OSI values of the patients with varicocele or azoospermia were significantly higher than those without either varicocele or azoospermia (p < 0.05)." (PMID 37476898, 2023).
age (11 papers, 2016 to 2025). A temporal measurement of the time period elapsed since an identifiable point in the life cycle of an organism. "Prior studies have demonstrated that inflammatory cytokines such as TNF-α and IL-1β can impair osteoblast function and promote osteoclast-mediated bone resorption, accelerating age-related bone loss." (PMID 41247564, 2025). "Resistance training has been reported to mitigate age-related chronic inflammation in skeletal muscle by reducing the expression of cytokines such as TNFα and IL-1β." (PMID 40529358, 2025). "Age-related neuroinflammation is characterized by increased levels of pro-inflammatory cytokines, such as interleukin (IL)-1β, as suggested by Norden and Godbout (2013)." (PMID 37397443, 2023). "The authors suggest that synapticsensitivity to IL-1β and that IL-1β function might evolve withage and with the appearance of age-related brain inflammationand elevation of proinflammatory molecules." (PMID 33415308, 2020).
alcoholic hepatitis (11 papers, 2020 to 2025). Acute hepatitis resulting from ingestion of alcohol. "IL-1β is also an inflammatory cytokine, and its levels are significantly increased in the liver and the serum in patients with alcoholic hepatitis." (PMID 36144575, 2022). "Canakinumab, a monoclonal antibody selectively inhibiting IL‐1β, has been tested in alcoholic hepatitis in a phase 2 RCT, where it led to histological improvements on liver biopsy but this did not translate into improved survival or Model for End‐Stage Liver Disease (MELD) score (NCT03775109)." (PMID 36800487, 2025). "While IL-1β plays a central role in hepatic inflammation and is significantly elevated in AH patients (almost 10-fold), the pathophysiology of alcoholic hepatitis involves an intricate network of interconnected mechanisms that cannot be addressed by targeting a single inflammatory pathway." (PMID 40724608, 2025). "Consequently, administration of IL-1β-antagonists proved to be protective in a mouse model of acute alcoholic hepatitis." (PMID 32751707, 2020). "In the MOD group, intervention with COST and COSM led to a reduction in serum levels of the inflammatory cytokines TNF-α, IL-1β, and IL-6 in the mice, suggesting that both compounds may ameliorate alcoholic hepatitis, albeit with COSM exhibiting slightly superior efficacy compared to COST." (PMID 40137320, 2025).
alcoholic steatohepatitis (11 papers, 2014 to 2026). "In other words, such nanobiologics counteracted GSDMD-mediated release of pro-inflammatory cytokine IL-1β to retard progression of alcoholic steatohepatitis." (PMID 39253076, 2024). "IL-1β has an established role in alcoholic steatohepatitis, and attenuation of liver injury is observed with IL-1R-/- mice and treatment with an IL-1R antagonist." (PMID 32498372, 2020). "Moreover, berberine diminished inflammation and lowered the levels of TNF-α, IL-6, and IL-1β in rats with non-alcoholic fatty liver disease by regulating the TLR4/MyD88/NF-κB signaling pathway." (PMID 38790653, 2024). "During progression of alcoholic steatohepatitis, GSDMD pore formation is critical to the excessive release of IL-1β from ethanol or acetaldehyde-stimulated macrophages." (PMID 39253076, 2024).
aspergillosis (11 papers, 2010 to 2025). Aspergillosis is an infection, growth, or allergic response caused by the Aspergillus fungus. "Corroborating this concept, intact IL-1β processing and release in caspase-11-deficient mice was also reported in aspergillosis." (PMID 31425553, 2019). "Individuals carrying the T-allele at P268S, which was associated with a reduced susceptibility to aspergillosis in patients, induced significantly lower IL-1β and demonstrated a trend toward lower TNF production in response to Aspergillus stimulation." (PMID 29980664, 2018). "Studies have shown that host immunity against disseminated candida, aspergillosis, and pneumocystis infection relies on IL-1β to clearly mount an adequate immune response, particularly in early stages of disease." (PMID 29170665, 2017). "IL-37 markedly reduced NLRP3-dependent neutrophil recruitment and steady state mRNA levels of IL-1β production and mitigated lung inflammation and damage in a relevant clinical model, namely aspergillosis in mice with cystic fibrosis." (PMID 25375146, 2014). "As uncontrolled IL-1β promotes detrimental neutrophil-dependent inflammation during aspergillosis, we examined whether IL-37 pretreatment affects the level of IL-1β production and inflammasome activation." (PMID 25375146, 2014). "Patients carrying the C allele showed a trend towards increased IL-1β and decreased IL-1Ra BAL levels compared to carriers of the homozygous reference TT genotype suggesting that this polymorphism (rs5744174) influences pulmonary inflammation during aspergillosis." (PMID 33510868, 2021). "We have therefore added another piece of evidence to support the role of IL-1B in CPA, that is, IL-1B is important not only in the pathogenesis of aspergillosis, but also in the activity of this particular disease." (PMID 30363691, 2018). "In contrast, inflammasome assembly during aspergillosis has never been described, although previous studies showing secretion of IL-1β by THP-1 during infection by A. fumigatus suggest that an inflammasome and caspase-1 must be activated." (PMID 20368800, 2010).
C. perfringens infection (11 papers, 2019 to 2025). "Compared to the CON group, C. perfringens infection significantly elevated serum levels of IL-1β, IL-6, and TNF-α, while suppressing IL-4 and IL-10 (p < 0.05)." (PMID 40427288, 2025). "In line with earlier findings in piglets and IPEC-J2 cells, we observed that C. perfringens infection significantly increased the serum levels of IL-1β, IL-6, and TNF-α, while decreasing those of IL-4 and IL-10." (PMID 40427288, 2025). "High and Medium dose C. perfringens infection significantly increased (P < 0.05) the concentration of IL-1β, IL-6, and TNF-α compared with Control group." (PMID 35769317, 2022). "The increase in NO production and iNOS activity and increased expression of pro-inflammatory cytokines, such as IL-1β, IL-6, iNOS, and IFN-γ demonstrate that C. perfringens infection induces a strong inflammatory response and causes severe tissue damage." (PMID 33679724, 2020). "Taken together, these results indicated that C. perfringens infection induces inflammasome activation and pyroptosis, a form of proinflammatory cell death of macrophages, with release of IL-1β." (PMID 31708887, 2019). "Nevertheless, we found that transcriptional levels of IL-1β, iNOS, and IFN-γ in the jejunum were up-regulated by coccidia and C. perfringens infection on both days 13 and 19, indicating strong inflammatory responses in the jejunum of birds." (PMID 38136901, 2023). "Additionally, C. perfringens infection induced expression of OPN, IL-1β, and IFN-γ genes at 1 dpi (day-post C. perfringens infection)." (PMID 38455042, 2024). "To clarify how LPS priming affects inflammasome activation in cells with C. perfringens infection, we examined the activation level of caspase-1 and IL-1β in the infected BMDMs primed or not primed with LPS." (PMID 31708887, 2019).
celiac disease (11 papers, 2015 to 2025). An autoimmune genetic disorder with an unknown pattern of inheritance that primarily affects the digestive tract. "Furthermore, TLRs overexpression has been associated to celiac disease, and accordingly to this observation, the stimulation of PBMCs from celiac patients with pepsin digest of wheat gliadin fraction led to IL-1β secretion via TLR4/MyD88/TRIF/MAPK/NF-kB signaling pathway." (PMID 29795662, 2018). "In patients with Celiac disease, the involvement of products downstream of the inflammasome activation, such as IL-1β and IL-18, was demonstrated." (PMID 39684769, 2024). "IL1β levels are increased in celiac disease, and together with TNF and IFNG, it favours intestinal permeability, a characteristic feature of celiac disease." (PMID 37175481, 2023). "In fact, an abnormal activation of NLRP1 and/or NLRP3 inflammasomes results in an altered activation of IL-1β and NF-κB, contributing to the lack of immune tolerance common in Celiac disease." (PMID 39684769, 2024). "This speculation would be in line with a previous finding of significantly higher levels for IL-6, IL-13, IL-10, IL-1b, and TNF-α in combination with significantly lower 25(OH)D concentrations in screening-detected celiac disease cases compared with healthy controls." (PMID 34604278, 2021).